URB1 (URB1 ribosome biogenesis factor)
Synonyms: C21orf108; KIAA0539; NPA1
Tractability: PROTAC: ubiquitination databases record sites on it; its protein half-life has been measured.
Gene: Protein-coding gene on chromosome 21 (32,311,018 to 32,393,029, reverse strand). Ensembl gene ENSG00000142207.
Subcellular location: Nucleus, nucleolus
Subcellular location (Human Protein Atlas): Nucleoli fibrillar center
Gene Ontology:
Molecular function: RNA binding
Biological process: maturation of 5.8S rRNA from tricistronic rRNA transcript (SSU-rRNA, 5.8S rRNA, LSU-rRNA); maturation of LSU-rRNA from tricistronic rRNA transcript (SSU-rRNA, 5.8S rRNA, LSU-rRNA)
Cellular component: fibrillar center; nucleolus
Genetic constraint (gnomAD): Loss-of-function variants: 182 observed, 225.43 expected, observed/expected ratio (o/e) 0.81, 90% interval 0.71 to 0.91. The upper end of that interval is the gene's LOEUF score, 0.91, which puts it in group 3 of 6, group 1 being the genes least tolerant of losing a copy. Missense variants: 2,574 observed, 2,783.8 expected, observed/expected ratio (o/e) 0.92, 90% interval 0.89 to 0.95. Synonymous variants: 1,101 observed, 1,171.2 expected, observed/expected ratio (o/e) 0.94, 90% interval 0.89 to 0.99.
Homologues: Orthologues: chimpanzee URB1 (99% identical), macaque URB1 (95% identical), dog URB1 (83% identical), rabbit URB1 (81% identical), guinea pig URB1 (81% identical), pig URB1 (80% identical), mouse Urb1 (76% identical), rat Urb1 (76% identical), tropical clawed frog urb1 (50% identical), zebrafish urb1 (43% identical), Drosophila melanogaster CG12499 (18% identical), Caenorhabditis elegans urb-1 (6% identical).
Diseases named in the same sentence as URB1 in open-access papers:
URB1 is named in the same sentence as 11 diseases in open-access papers, as found by Europe PMC text mining. Sharing a sentence is not in itself a finding about the gene and the disease. The quoted sentences say what the papers report.
colorectal cancer (2 papers, 2020 to 2023). A primary or metastatic malignant neoplasm that affects the colon or rectum. "ATF4 is a downstream target of URB1 and is involved in the oncogenic role of URB1 in colorectal cancer.Our study demonstrated, for the first time, how transcriptional control of the SHH protein by ATF4 affects the development of gastric cancer." (PMID 36900220, 2023). "Regulatory associated protein with mammalian target of rapamycin (RAPTOR) contributes to colorectal cancer proliferation and cell cycle progression through positively regulating URB1 and cyclinA2 via activating mTOR complex 1 signaling." (PMID 31886628, 2020).
colon cancer (1 paper, 2020). "Given that URB1 is also overexpressed in colon cancer tissues according to TCGA dataset, we then assessed URB1 expression in TMA slides, and found that URB1 protein was expressed significantly higher in colon cancer tissues than normal tissues (P = .0033)." (PMID 31886628, 2020).
tuberculosis (1 paper, 2025). A chronic, recurrent infection caused by the bacterium Mycobacterium tuberculosis. "This study revealed that plasma URB1 levels were significantly elevated in patients with active tuberculosis and markedly decreased after treatment, suggesting a potential association between URB1 and disease activity in tuberculosis." (PMID 41428679, 2025).
neoplasia (2 papers, 2020 to 2025). "Protein expressions of p‐CDC2, cyclin B1 and URB1 in tumor samples were also evaluated in vivo, and the findings aligned with the in vitro results." (PMID 39673181, 2025). "Together, these findings indicated that RAPTOR promotes CRC tumorigenesis and progression by provoking mTORC1 and the transcriptional activation of URB1, which further supports the potential oncogenic role of mTORC1/RAPTOR‐URB1 axis in neoplasia." (PMID 31886628, 2020).
cancer (1 paper, 2020). A tumor composed of atypical neoplastic, often pleomorphic cells that invade other tissues. "Thus, we speculated that mTORC1/RAPTOR signaling may promote digestive malignant tumor proliferation and progression by activating the novel oncogene, URB1." (PMID 31886628, 2020).
URB1 also shares sentences with these, for which no sentence is quoted: Alzheimer disease (1 paper); behavioral disorders (1); Down syndrome (1); gastric cancer (1); glioma (1); infection (1).